IFITM2 (interferon induced transmembrane protein 2)
Diseases named in the same sentence as IFITM2 in open-access papers (continued):
Sharing a sentence is not in itself a finding about the gene and the disease.
cancer (15 papers, 2011 to 2026). A tumor composed of atypical neoplastic, often pleomorphic cells that invade other tissues. "IFITM2 thus possibly acts differently in various cancer types, but the cause of this variation is unknown." (PMID 36466909, 2022). "In this study, we confirmed that IFITM2 expression was present in 36 different types of cancer using data from the TCGA database." (PMID 38802621, 2024). "On the other hand, in vitro studies often describe that targeted IFITM1, IFITM2 and IFITM3 protein silencing in cancer cells causes proliferation inhibition, cell cycle arrest and senescence." (PMID 36466909, 2022). "IFITM2 is a potential biomarker in some cancers, but its functional mechanism is still elusive." (PMID 38802621, 2024). "According to TIMER analysis, IFITM2 was overexpressed in five types of cancer, including CRC." (PMID 38802621, 2024). "How IFITM2 regulate immune responses through NK cells is unknown in SARS-CoV-2-infected cancer patients." (PMID 36555339, 2022). "Moreover, interferon induces transmembrane protein 2 (IFITM2), thought to act as a tumor suppressor, promotes cancer cell proliferation, invasion, migration and the EMT in vitro, as well as tumor growth and metastasis in an xenograft model." (PMID 30111747, 2018). "In addition, IFITM2 also has the effect of promoting cancer." (PMID 36555339, 2022). "IFIT1 affects cancer cell behavior through Wnt/β-Catenin signaling, and IFITM1, IFITM2, and IFITM3 are related to antiviral functions." (PMID 38424218, 2024). "We next examined how overexpression of WT ENPP1 in cancer cells affected STING activation in cGAMP responder cells as measured by their combined Ifitm1, Ifitm2, and Ifitm3 expression (Ifitms)." (PMID 38117852, 2023). "To date, IFITM1, IFITM2 and IFITM3 overexpression has been described in various cancer cell lines and tissues." (PMID 36466909, 2022). "There was also a significant (p < 0.05) negative correlation between ESR1 gene expression and IFITM2 expression levels in Luminal A cancer patients." (PMID 39765744, 2024). "In addition, genes reported to be involved in immunological response to pathogens, such as IL-8, IFITM1, IFITM2, and RHOB were also significantly differentially expressed in cancer tissue." (PMID 38505585, 2024). "As shown in this study, inhibition of IFITM2 significantly inhibited PI3K/AKT activation in CRC cells, suggesting that the cancer-promoting effect of IFITM2 in CRC may be related to its regulation of the PI3K/AKT signaling pathway." (PMID 38802621, 2024). "Interestingly, the expression levels of Ifitm2 and Ifitm3, pivotal players in cellular antiviral defense, were elevated in PMN-MDSCs derived from cancer patients." (PMID 38919617, 2024). "The IFITM1, IFITM2 and IFITM3 proteins influence the epithelial–mesenchymal transition (EMT) status, cell migration, invasion and the presence of distant metastases, as has been shown in both in vitro and in vivo studies performed with various cancer cell lines, animal models and patient samples." (PMID 36466909, 2022). "However, knocking out IFITM2 could enhance the activation of the endogenous IFN-α pathway that may alter the immune and stromal cells in the TME enhancing the invasive abilities of cancer cells." (PMID 36500393, 2022).
cardiac diseases (1 paper, 2024). "Previous studies have also reported the involvement of IFIT2 and IFITM2 in cardiac diseases." (PMID 38355637, 2024).
IFITM2 also shares sentences with these, for which no sentence is quoted: Autoimmunity (2 papers); Arthritis (1); bacterial pneumonia (1); bile duct carcinoma (1); bladder cancer (1); bladder urothelial carcinoma (1); chronic hepatitis C virus infection (1); Cognitive impairment (1); dermatitis (1); encephalitis (1); endometrial cancer (1); Flavivirus Infections (1); heart failure (1); hematologic cancer (1); hepatoma (1); invasive breast carcinoma (1); juvenile dermatomyositis (1); lung carcinoma (1); lymphoma (1); metabolic disorders (1); Obesity (1); renal cell carcinoma (1); renal chromophobe cell carcinoma (1); Salmonella Infections (1); Shwachman-Bodian-Diamond syndrome (1); ZIKV infection (1).